FZD5 (frizzled class receptor 5)
Description:
Receptor for Wnt proteins. Functions in the canonical Wnt/beta-catenin signaling pathway. In vitro activates WNT2, WNT10B, WNT5A, but not WNT2B or WNT4 signaling (By similarity). In neurons, activation by WNT7A promotes formation of synapses. May be involved in transduction and intercellular transmission of polarity information during tissue morphogenesis and/or in differentiated tissues (Probable). Plays a role in yolk sac angiogenesis and in placental vascularization (By similarity). Plays a role in ocular development.
Synonyms: hFz5; C2orf31; DKFZP434E2135; MCOPCB11
Tractability: Small molecule: a structure with a bound ligand is known. Antibody: a drug acting on it is in phase 2 or 3 trials; UniProt places it where antibodies can reach, with high confidence; its Gene Ontology location is reachable by antibodies, with high confidence; UniProt predicts a signal peptide or a membrane-spanning region. PROTAC: UniProt records ubiquitination sites on it.
Target class: Frizzled family G protein-coupled receptor; Membrane receptor
Gene: Protein-coding gene on chromosome 2 (207,762,598 to 207,769,914, reverse strand). Ensembl gene ENSG00000163251.
Subcellular location: Cell membrane; Golgi apparatus membrane; Synapse; Perikaryon; Cell projection, dendrite; Cell projection, axon
Pathways (Reactome):
Signal Transduction: Asymmetric localization of PCP proteins; Ca2+ pathway; Class B/2 (Secretin family receptors); Disassembly of the destruction complex and recruitment of AXIN to the membrane; Regulation of FZD by ubiquitination; WNT5A-dependent internalization of FZD2, FZD5 and ROR2
Disease: Signaling by RNF43 mutants
Gene Ontology:
Molecular function: amyloid-beta binding; protein binding; protein kinase binding; protein-containing complex binding; ubiquitin protein ligase binding; Wnt receptor activity; Wnt-protein binding; transmembrane signaling receptor activity
Biological process: anterior/posterior axis specification, embryo; canonical Wnt signaling pathway; cellular response to molecule of bacterial origin; embryonic axis specification; eye development; non-canonical Wnt signaling pathway; positive regulation of establishment of protein localization to mitochondrion; positive regulation of T cell cytokine production; positive regulation of transcription by RNA polymerase II; positive regulation of type II interferon production; regulation of mitophagy; Spemann organizer formation; neuron differentiation; positive regulation of interleukin-1 beta production; positive regulation of tumor necrosis factor production; synapse assembly; cell surface receptor signaling pathway; embryonic camera-type eye morphogenesis; system development
Cellular component: cell surface; plasma membrane; clathrin-coated endocytic vesicle membrane; early endosome membrane; Golgi membrane; perikaryon; synapse; axon; bicellular tight junction; dendrite; early endosome; Golgi apparatus; membrane; perinuclear region of cytoplasm
Genetic constraint (gnomAD): Loss-of-function variants: 12 observed, 35.31 expected, observed/expected ratio (o/e) 0.34, 90% interval 0.22 to 0.55. The upper end of that interval is the gene's LOEUF score, 0.55, which puts it in group 2 of 6, group 1 being the genes least tolerant of losing a copy. Missense variants: 622 observed, 780.6 expected, observed/expected ratio (o/e) 0.8, 90% interval 0.75 to 0.85. Synonymous variants: 380 observed, 360.22 expected, observed/expected ratio (o/e) 1.05, 90% interval 0.97 to 1.15.
Homologues: Orthologues: chimpanzee FZD5 (99% identical), macaque FZD5 (99% identical), dog FZD5 (97% identical), rabbit FZD5 (97% identical), mouse Fzd5 (97% identical), rat Fzd5 (97% identical), pig FZD5 (96% identical), guinea pig FZD5 (96% identical), zebrafish fzd5 (71% identical), Drosophila melanogaster fz2 (58% identical), Caenorhabditis elegans cfz-2 (37% identical), Drosophila melanogaster fz3 (24% identical), and 1 more. Paralogues in human: FZD8 (69% identical), FZD2 (48% identical), FZD7 (47% identical), FZD1 (46% identical), FZD10 (43% identical), FZD9 (42% identical), FZD4 (39% identical), FZD3 (36% identical), FZD6 (34% identical), SMO (26% identical), SFRP4 (16% identical), FRZB (15% identical), and 3 more.
Diseases named in the same sentence as FZD5 in open-access papers:
FZD5 is named in the same sentence as 93 diseases in open-access papers, as found by Europe PMC text mining. Sharing a sentence is not in itself a finding about the gene and the disease. The quoted sentences say what the papers report.
pancreatic cancer (10 papers, 2014 to 2025). "FZD5 mainly expressed in RNF43 mutated tumor cells was proposed as a molecular target for pancreatic cancer treatment." (PMID 33291655, 2020). "miR-29c is associated with both Fzd4 and Fzd5 in pancreatic cancer." (PMID 34671643, 2021). "Cholesterol binds to the LS3 segment in the linker region of Fzd5, facilitating its palmitoylation at the C538 site in pancreatic cancer cells." (PMID 39809787, 2025). "This study reveals that cholesterol specifically binds to Fzd5 and enables Fzd5 maturation to activate Wnt/β‐catenin signaling which is required for pancreatic cancer." (PMID 35975457, 2022). "Circ_0067934 inhibits miR-1324, an miRNA that decreases Fzd5 expression and downstream Wnt/β-catenin signaling in pancreatic cancer." (PMID 34671643, 2021). "A genome-wide CRISPR screening approach identified a druggable Wnt-FZD5 signaling circuit as a critical vulnerability specific to RNF43-mutant pancreatic tumors, revealing a potential therapeutic strategy for this genetically defined subset of pancreatic cancers." (PMID 39936971, 2025). "Moreover, FZD5 has been identified as a dominant FZD receptor in RNF43-mutant pancreatic cancer cells and may be a therapeutic index." (PMID 33291655, 2020). "miR-29c decreases expression of Fzd4, Fzd5, and frizzled co-receptor LRP6, inhibiting pancreatic tumor cell migration and stemness." (PMID 34671643, 2021). "Two pancreatic cancer cell lines, PaTu8988s and HPAF-II, are known to express high levels of FZD5." (PMID 37943878, 2023).
hepatocellular carcinoma (9 papers, 2021 to 2023). A malignant tumor that arises from hepatocytes. "For instance, circ_0067934 has been demonstrated to promote the growth and metastasis of Hepatocellular carcinoma (HCC) by modulating the miR-1324/FZD5/Wnt/β-catenin axis." (PMID 37592109, 2023). "Other findings also demonstrated that circ_0067934 promotes tumor growth and metastasis in hepatocellular carcinoma through regulation of the miR-1324/FZD5/Wnt/β-catenin axis." (PMID 33958507, 2021). "Circ_0067934 directly suppressed miR‐1324, which targeted the 3'‐UTR of FZD5 mRNA and subsequently down‐regulated the Wnt/β‐catenin signalling pathway in hepatocellular carcinoma." (PMID 34697900, 2021). "For example, circ_0067934 is upregulated in both tissues and cells of hepatocellular carcinoma and promotes metastasis through miR-1324/FZD5/Wnt/β-catenin pathway." (PMID 34329193, 2021). "In hepatitis B virus (HBV)-associated hepatocellular carcinoma, the hsa_circ_0067934 acts as a sponge for the miR-1324, thus, altering the FZD5/Wnt/β-catenin signalling pathway, which participates in the proliferation, migration, and invasion of the HBV-associated hepatocellular carcinoma." (PMID 38003737, 2023). "miR-1324 is involved in the circ_0067934/Fzd5 axis in hepatocellular carcinoma (HCC)." (PMID 34671643, 2021). "In addition, studies have found that CIRC_0067934 directly inhibits the interaction between mRNA 3′-UTR of FZD5 and miR-1324 and activates the FZD5/Wnt/β-catenin signal pathway to promote the proliferation, invasion, and migration of hepatocellular carcinoma cells." (PMID 33884267, 2021). "In hepatocellular carcinoma (HCC), YTH domain containing family protein-1 (YTHDF1) facilitates EMT in part by increasing translation of FZD5 and activating canonical β-catenin signaling." (PMID 34604862, 2021).
prostate carcinoma (9 papers, 2012 to 2025). A carcinoma that arises from epithelial cells of the prostate gland. "Another study linked FZD5 to the aggressiveness of prostate cancer." (PMID 29930766, 2018). "In a recent study on long non-coding RNAs (lncRNAs), LINC00115 was shown to induce prostate cancer cell proliferation via the miR-212-5p/FZD5/Wnt/β-catenin axis, in which Fzd8 leads to the activation of the canonical Wnt pathway." (PMID 41465498, 2025). "Increased expression of FZD5 was shown to be implicated in cancer development and metastasis by over-activation of canonical Wnt pathways in various cancers including HCC and prostate cancers." (PMID 36483915, 2022). "Rescue experiments further showed that LINC00115 inhibits prostate cancer cell proliferation and invasion via targeting miR‐212‐5p/ FZD5/ Wnt/β‐catenin axis." (PMID 34697900, 2021). "Previous studies showed that knockdown FZD5 gene can inhibit migration, invasion and bone metastasis of prostate cancer cells." (PMID 34697900, 2021). "FZD5 has been identified to be a preferred receptor of Wnt5a, which mediates the antiproliferative and proapoptotic effects in prostate cancer, and inflammatory reactions in sepsis." (PMID 34564708, 2021). "Collectively, these data suggested that down‐regulated LINC00115 inhibits prostate cancer cell proliferation and invasion via targeting miR‐212‐5p/ FZD5/ Wnt/β‐catenin axis." (PMID 34697900, 2021). "In another example, FZD5 is involved in prostate cancer, which is the most common malignancy in older men." (PMID 31706268, 2019). "The mRNA expression level of FZD5 was significantly higher in stage II prostate cancer patients compared to healthy controls and higher prostate cancer stages (p<0.01; p<0.001, respectively)." (PMID 29930766, 2018). "Taken together, the data suggest a more prominent role of WNT5A/FZD5 than WNT5A/RYK signaling in prostate cancer." (PMID 29930766, 2018). "Our study now extends these data identifying high FZD5 protein levels in prostate cancer tissue as well." (PMID 29930766, 2018). "Silencing of FZD5 diminishes prostate cancer burden in vivo, which was confirmed by our results in vitro." (PMID 29930766, 2018). "Further correlation analysis with clinicopathological markers for prostate cancer revealed a significant correlation of FZD5 expression and the PSA level (r=0.01104, p=0.028) and between RYK-ICD and GS (r=0.1468, p=0.003)." (PMID 29930766, 2018). "We also innovatively uncovered that LINC00115 endogenously sponged miR‐212‐5p to elevate FZD5 expression, thus facilitating the malignant phenotype of prostate cancer, which might provide new insight into identifying the biomarkers for prostate cancer." (PMID 34697900, 2021). "Moreover, we have previously shown that FZD5 mRNA expression is upregulated in human prostate cancer and correlates with WNT5A expression." (PMID 29930766, 2018). "Besides prostate cancer FZD5 is downregulated in endometrial adenocarcinoma." (PMID 29930766, 2018). "Amongst all FZD receptors, FZD5 was one of the most highly expressed receptors in the prostate cancer cell lines and WNT5A also showed a stronger binding response to FZD5 than to RYK." (PMID 29930766, 2018). "Extensive in vitro analyses revealed that the WNT5A receptors FZD5 and RYK mediate the anti-tumor effects of WNT5A on prostate cancer cells." (PMID 29930766, 2018). "In conclusion, WNT5A/FZD5 and WNT5A/RYK signaling are both involved in mediating the pro-apoptotic and anti-proliferative effects of WNT5A in prostate cancer." (PMID 29930766, 2018). "In conclusion, this study suggests that FZD5 and RYK are the predominant receptors for mediating the pro-apoptotic and anti-proliferative effects of WNT5A in prostate cancer in vitro." (PMID 29930766, 2018).
prostate carcinoma (continued). "By analyzing the expression of known WNT5A receptors in five different prostate cancer cell lines, performing functional assays, and validating receptor expression in a large set of human samples, we found the receptors FZD5 and RYK mediate anti-tumor effects of WNT5A in prostate cancer." (PMID 29930766, 2018). "Moreover, FZD5 and WNT5A co-expression exhibits potential as disease specific survival marker for prostate cancer patients." (PMID 29930766, 2018).
melanoma (7 papers, 2009 to 2022). A malignant, usually aggressive tumor composed of atypical, neoplastic melanocytes. "For example, Fzd5/Wnt5a activates the Ca2+ pathway in melanoma and is associated with a more aggressive phenotype, whilst in the developing retina Fzd5 signals via β-catenin." (PMID 27196929, 2016). "FZD5 was down-regulated in response to differentiation of NT2/D1 cells and in human melanoma cells FZD5 activation by WNT5A had been associated with elevated metastatic potential." (PMID 19874621, 2009). "Antibodies against FZD5 have been shown to be able to block melanoma cell migration and invasion in vitro, possibly by the inhibition of PKC activity." (PMID 36620565, 2022). "In line with our findings here, it has been reported that Wnt5A/FZD-5 signaling increased melanoma cell adhesion and migration, which was reversed in the presence of Box537,39." (PMID 33723319, 2021). "Thus, while Fzd5 expression is variable in non-melanoma skin cancer cells, its expression level in tumor-vessels is consistent with a role of this receptor in mediating Wnt5a-dependent inflammatory pathways, consistent with previous reports." (PMID 22384081, 2012). "In addition, motility and invasion of melanoma cells is increased through WNT5A/FZD5 signaling." (PMID 29930766, 2018). "Due to the caveats of the specificity of the chemical inhibitors or blocking antibodies, further studies are needed to directly determine the function of FZD5 and FZD8 in melanoma." (PMID 36620565, 2022). "The role of FZD5 and FZD8 in melanoma has not been studied directly." (PMID 36620565, 2022).
ovarian carcinoma (7 papers, 2015 to 2025). A malignant neoplasm originating from the surface ovarian epithelium. "Since Wnt signaling is implicated in many type of tumors including ovarian cancer we further investigated regulation of FZD5 by ARID3B." (PMID 26121572, 2015). "Fzd5 acts in a tumorigenic nature in ovarian cancer, as increased FZD5 expression is associated with increased expression of ECM components related to EMT processes, such as fibronectin and vitronectin, while the loss of FZD5 presented a decrease in the ECM components." (PMID 34604862, 2021). "In summary, we hypothesize here, that Wnt5A/FZD-5 signaling modulate αv integrin expression levels that could be associated with ovarian cancer cell proliferation, migration, and fibronectin attachment." (PMID 33723319, 2021). "Recently, FZD5 has been reported to induce stemness and HR repair in ovarian cancer cells resistant to DNA-damaging agents." (PMID 40001953, 2025). "In ovarian cancer cells, the knockdown of FZD5 downregulated the expression of active β-catenin through Akt." (PMID 40001953, 2025). "What is important, we found that the expression of CCL15 and FZD5 was relatively low expressed in ovarian cancer cell lines, which also showed relative small proportion weight in the signature." (PMID 35769811, 2022). "To assess if ARID3B modulates changes in adhesion potentially through Wnt signaling, we tested the effects of ARID3B or FZD5 expression in ovarian cancer cells on adhesion to ECM components." (PMID 26121572, 2015). "Overexpression of FZD5 or ARID3B in ovarian cancer cells increases adhesion to several ECM proteins, including fibronectin and vitronectin, while knockdown of FZD5 or editing of ARID3B causes a loss of adhesion to certain ECM components." (PMID 26121572, 2015). "WNT5A and FZD5 are overexpressed in ovarian cancer and correlate with poor prognosis, and Wnt activity is known to regulate cell proliferation and death." (PMID 26121572, 2015). "Wnt signaling enhances tumor cell proliferation and tumor development, and FZD5 expression correlates with poor prognosis in ovarian cancer." (PMID 26121572, 2015). "We showed that FZD5 is overexpressed in ovarian cancer cell lines compared to IOSE398 cells; this finding agrees with studies of ovarian cancer which find that FZD5 expression correlates with advanced malignancy." (PMID 26121572, 2015). "FZD5 is highly expressed in ovarian cancer cell lines, and is upregulated by exogenous ARID3B." (PMID 26121572, 2015). "In our study, we found the signature-related genes such as AXL, FZD5, POLR3H, and MED1 were related to the immune cell expressions in ovarian cancer." (PMID 35769811, 2022). "It should be noted that in all of our experiments using ovarian cancer cell lines (OVCA429, Skov3IP, Skov3, and OVCAR3) it was necessary to use lentiviral transduction to introduce 6xHis-ARID3B, RFP, or FZD5 into the cells." (PMID 26121572, 2015). "The consistent induction of FZD5 and MYC is especially interesting, considering that both are frequently expressed at high levels in ovarian cancer cells compared to immortalized ovarian surface epithelial cells (IOSE398)." (PMID 26121572, 2015). "Thus, we found that the expression of FZD5 and MED1 correlated with the age, and CCL15 correlated with lymphatic invasion in ovarian cancer." (PMID 35769811, 2022). "TCF/LEF induced transcriptional activity is induced by ARID3B transfected 293FT cells, but since we were unable to perform TOPFlash assays in our ovarian cancer cells we do not know if ARID3B activation of FZD5 results in TCF/LEF mediated gene expression." (PMID 26121572, 2015).
breast carcinoma (5 papers, 2016 to 2024). "Loss and gain of function studies confirmed that FZD5 modulated these factors in breast cancer cells." (PMID 33311446, 2020). "In publicly available human breast cancer expression data, FZD5, 6, 7, and 9 are expressed at higher levels in basal-like breast cancer cases than other subtypes." (PMID 37943878, 2023). "In summary, our study has demonstrated a novel function of FZD5 in breast cancer, especially in TNBC." (PMID 33311446, 2020). "The Cancer Genome Atlas (TCGA) database was interrogated for FZD5 mRNA expression in breast cancer tissues." (PMID 33311446, 2020). "Our previous study revealed that FZD5 modulates ALDH+ stem-like cells in breast cancer." (PMID 38539211, 2024). "Furthermore, knockout of FZD-5 robustly inhibited cell growth in breast cancer cells and RNF43-mutant pancreatic ductal adenocarcinoma cells." (PMID 33723319, 2021). "FZD5 knockdown weakened the mammosphere formation capacity of breast cancer cells." (PMID 33311446, 2020). "Interrogation of CCLE database revealed a positive correlation of FZD5 with FOXM1, BRCA1, and BIRC5, several key factors related to cell cycle, DNA replication, DNA damage repair, and survival, in a total of 57 breast cancer cell lines." (PMID 33311446, 2020).